MIR378D2 (microRNA 378d-2)
Synonyms: hsa-mir-378d-2; mir-378d-2
Gene: MicroRNA gene on chromosome 8 (93,916,022 to 93,916,119, reverse strand). Ensembl gene ENSG00000284288.
Homologues: Orthologues: chimpanzee MIR378D2 (100% identical), mouse Gm54396 (28% identical), rat Mir3557 (28% identical), macaque mml-mir-378d (24% identical). Paralogues in human: MIR378A (32% identical), MIR378B (29% identical).